NEAT1 (nuclear paraspeckle assembly transcript 1)
Diseases named in the same sentence as NEAT1 in open-access papers (continued):
Sharing a sentence is not in itself a finding about the gene and the disease.
Hypertension (2 papers, 2021 to 2023). The presence of chronic increased pressure in the systemic arterial system. "LncRNAs NEAT1, GAS5, and HOTAIR have previously been linked to the risk and development of CVS, and to pathologic vasculature remodeling in response to hypertension, which is the primary risk factor for cerebrovascular dysfunction." (PMID 36439973, 2023). "ROC curve analysis for the NEAT1, HOTAIR, and GAS5 revealed statistically significant differences in CVS patients, whether they had hypertension or not, when compared to controls, with fair sensitivity and high specificity, implying their diagnostic values." (PMID 36439973, 2023).
infertile (2 papers, 2014 to 2022). "We discovered two lncRNAs associated to infertility in the LncRNADisease database: H19 and NEAT1." (PMID 35419445, 2022).
ischemic disease (2 papers, 2022 to 2023). Lack of blood supply to an area of the body, resulting in impairment of tissue oxygenation. "NEAT1 has been extensively studied as a cancer regulator, and a number of studies have recently examined the link between NEAT1 and vascular and ischemic diseases." (PMID 36439973, 2023). "Neat1, as a stress-induced lncRNA, plays a role in many pathologies including cancer and ischemic diseases, thus its central role in the translational control of expression of genes involved in tissue revascularization and cell survival makes it a potential therapeutic target of great interest." (PMID 36546462, 2022).
joint disease (2 papers, 2023 to 2024). "To test this hypothesis, we first investigated the expression of H19, Neat1 lncRNAs and their target genes in an arthropathy model of haemophilia mice." (PMID 37183540, 2023).
kidney stone (2 papers, 2021 to 2024). "Moreover, the elevated expression of ceRNAs such as NEAT1, PVT1, hsa-miR-23b-3p, hsa-miR-429, hsa-miR-139-5p, CCL7, and ROBO2, along with the presence of infiltrating immune cells like Mps and mast cells, may be associated with the development of kidney stones." (PMID 38397450, 2024). "The results indicated that significant expressions of ceRNAs (NEAT1, PVT1, hsa-miR23b-3p, hsa-miR-429, hsa-miR-139-5p, CCL7, and ROBO2) and infiltrating immune cells (Mps and mast cells) may be involved in the pathogenesis of kidney stones." (PMID 38397450, 2024).
multiple endocrine neoplasia type 1 (2 papers, 2020 to 2023). An autosomal dominant tumor predisposition syndrome caused by pathogenic variants in the MEN1 gene, characterized by an increased risk of tumors of the parathyroid glands, pituitary gland, and foregut neuroendocrine tumors (most commonly pancreatic islet cells). "Among numerous tumor-related lncRNAs, whose length ranges from 200nt to 100kb without capacity of protein-coding function, nuclear enriched abundant transcript 1 (NEAT1) is a novel lncRNA localized specifically to nuclear paraspeckles and transcribed from multiple endocrine neoplasia type 1 locus." (PMID 33202380, 2020).
Nephropathy (2 papers, 2021 to 2023). A nonspecific term referring to disease or damage of the kidneys. "In addition, it is noteworthy that by analyzing lncRNA studies performed on renal diseases, we can identify six lncRNAs involved in more than one type of renal disease, in particular PVT1, TUG1, NEAT1, MALAT1, XIST, and H19." (PMID 37190024, 2023).
periodontitis (2 papers, 2022 to 2024). An acute or chronic inflammatory process that affects the tissues that surround and support the teeth. "Since inflammatory plays important roles in periodontitis progression, we aimed to explore the role of NEAT1 in chronic periodontitis (CP) in vitro." (PMID 35034548, 2022). "Silencing of NEAT1 and over-expression of miR-200c-3p enhanced cell viability and repressed apoptosis in the periodontitis model group." (PMID 35034548, 2022). "In this research, NEAT1 is up-regulated in CP tissues and periodontitis model group." (PMID 35034548, 2022). "Importantly, a study has reported dysregulation of lncRNA NEAT1 in gingival tissues or blood samples of patients with periodontitis in comparison with healthy subjects." (PMID 35034548, 2022).
polycystic ovary syndrome (2 papers, 2022). A disorder that manifests as multiple cysts on the ovaries. "NEAT1 interference-mediated effect induces proliferation and represses apoptosis of ovarian granulosa cells in polycystic ovary syndrome via the microRNA-381/IGF1 axis." (PMID 36523600, 2022).
prostate adenocarcinoma (2 papers, 2019 to 2025). "In the study of prostate cancer (PRAD), an extensive examination of a large group of clinical patient data revealed a notable correlation between the expression levels of lncRNA - NEAT1 and the advancement of prostate adenocarcinoma (PRAD)." (PMID 40110044, 2025).
rosacea (2 papers, 2020 to 2025). A chronic erythematous skin disorder that affects the face. "Our data suggest that NEAT1 may cause damage in rosacea by regulating genes associated with immune dysregulation and inflammation, as indicated by NEAT1-regulated genes that are enriched in chemokine activity, which play crucial roles in inflammatory infiltration." (PMID 32185228, 2020). "Upregulated NEAT1 can be a possible biomarker for rosacea diagnosis as well as HOTAIR and ZNF667-AS1 can be a target for rosacea prevention and treatment." (PMID 32185228, 2020). "Here, for the first time, it was identified a relationship between the NEAT1 and rosacea." (PMID 32185228, 2020). "In addition, we found nine differentially expressed lncRNAs in all three rosacea subtype-related networks, including NEAT1 and HOTAIR, which may play important roles in the pathology of rosacea." (PMID 32185228, 2020). "The results by RT-qPCR revealed the increased expression of NEAT1 and decreased expression of HOTAIR, ZNF667-AS1 in rosacea tissues, which was consistent with microarray." (PMID 32185228, 2020). "FISH staining (Merge) confirmed the increased expression of NEAT1 and decreased expression of HOTAIR and ZNF667-AS1 in rosacea compared to normal adjacent specimens." (PMID 32185228, 2020).
sarcoma (2 papers, 2019 to 2020). A usually aggressive malignant neoplasm of the soft tissue or bone.
Seizure (2 papers, 2017 to 2026). A seizure is an intermittent abnormality of nervous system physiology characterized by a transient occurrence of signs and/or symptoms due to abnormal excessive or synchronous neuronal activity in the brain. "We then extended these initial observations with an additional 14 seizure patient samples, and found that these also display significantly up-regulated NEAT1 expression in high versus low activity regions resected from the brains of affected individuals." (PMID 28054653, 2017).
abscesses (1 paper, 2022). "The data showed that the high expression of lncRNA NEAT1 was associated with paraspinal abscesses, segments of the lesions, and duration of anti-TB chemotherapy." (PMID 35465262, 2022). "The expression of lncRNA NEAT1 was related to segments of the lesions, paraspinal abscesses, anti-TB treatment, drug resistance, interleukin-6 (IL-6), C-reactive protein (CRP), and erythrocyte sedimentation rate (ESR)." (PMID 35465262, 2022).
acute leukemia (1 paper, 2025). A clonal (malignant) hematopoietic disorder with an acute onset, affecting the bone marrow and the peripheral blood. "NEAT1 is a lincRNA gene that acts as a tumor suppressor in acute leukemia, and its expression level directly affects the differentiation of white blood cells." (PMID 40699783, 2025).
adenoma (1 paper, 2026). A neoplasm arising from the epithelium. "CCAT1, HOTAIR, and NEAT1 were significantly upregulated in CRC patients compared with adenoma patients and healthy controls (all p < 0.001)." (PMID 42193038, 2026).
anemia (1 paper, 2025). A reduction in the number of red blood cells, the amount of hemoglobin, and/or the volume of packed red blood cells. "Only NEAT1 demonstrated diagnostic accuracy in distinguishing between patients based on the presence of anemia, with 85.71% sensitivity and 78.43% specificity (AUC = 0.84; cut-off > 0.28; p < 0.001)." (PMID 40150019, 2025). "In patients with post-RT anemia (hemoglobin < 12 g/dL), both low MALAT1 (median: 0.31 vs. 0.44; p = 0.023) and NEAT1 expression (median: 0.30 vs. 0.43; p = 0.008) were observed compared to those with normal hemoglobin levels." (PMID 40150019, 2025).
Anxiety (1 paper, 2020). Intense feelings of nervousness, tension, or panic often arise in response to interpersonal stresses. "Surprisingly, Neat1−/− mice displayed dramatically reduced activity, as compared to Neat+/+ mice, in the first 2 h of the test, i.e., when the animals encountered novel conditions, suggestive of increased anxiety." (PMID 32467583, 2020).
Azoospermia (1 paper, 2025). Absence of any measurable level of sperm,whereby spermatozoa cannot be observed even after centrifugation of the semen pellet. "This study is designed to determine the roles of NEAT1 and miR-34a as diagnostic and susceptibility biomarkers for non-obstructive azoospermia and severe oligospermia." (PMID 40165339, 2025). "This study highlights the promise of serum NEAT1 and miR-34a as diagnostic markers for non-obstructive azoospermia and severe oligospermia." (PMID 40165339, 2025). "This study highlights the diagnostic potential of serum NEAT1 and miR-34a for non-obstructive azoospermia and severe oligospermia." (PMID 40165339, 2025). "However, research on the association between the lncRNA NEAT1 and non-obstructive azoospermia is limited." (PMID 40165339, 2025). "Our results provide preliminary evidence regarding the potential role of the NEAT1/miR-34a/SIRT1 axis, highlighting its possible relevance in understanding the molecular mechanisms underlying non-obstructive azoospermia and oligozoospermia." (PMID 40165339, 2025). "This study assessed the expression levels of ncRNAs NEAT1 and miR-34a in the serum of patients with non-obstructive azoospermia and severe oligospermia compared to those with normal fertility." (PMID 40165339, 2025). "This study aimed to compare the serum levels of NEAT1 and miR-34a in men with infertility, specifically those with non-obstructive azoospermia or severe oligospermia, against those of fertile men." (PMID 40165339, 2025). "We evaluated NEAT1 expression in both non-obstructive azoospermia and severe oligospermia groups." (PMID 40165339, 2025). "Additionally, NEAT1 levels were significantly reduced in those with severe oligospermia compared to non-obstructive azoospermia patients (p = 0.0276)." (PMID 40165339, 2025). "However, in the non-obstructive azoospermia group, NEAT1 was downregulated, but the difference was not statistically significant compared to the fertile male group results." (PMID 40165339, 2025). "In the case of non-obstructive azoospermia, serum NEAT1 levels also successfully distinguished these patients from healthy controls, yielding an AUC of 0.6762 (95% CI: 0.7820 to 0.9977, p = 0.01), with 52% sensitivity and 95% specificity at a cutoff above 1.29." (PMID 40165339, 2025). "Although the combination of NEAT1 and miR-34a with other biomarkers, such as specific hormones, may aid in non-obstructive azoospermia and severe oligospermia diagnosis, this needs further investigation." (PMID 40165339, 2025).
B-cell neoplasm (1 paper, 2022). A group of heterogeneous lymphoid tumors generally expressing one or more B-cell antigens or representing malignant transformations of B-lymphocytes. "While functions of the majority of identified lncRNA are poorly studied, some of them (e.g., NEAT1 and MALAT1) play a role in development of B-cell neoplasms." (PMID 36275462, 2022).
bacterial pneumonia (1 paper, 2024). Acute infection of the lung parenchyma caused by bacteria (e.g., Streptococcus pneumoniae, Haemophilus influenzae, Chlamydia pneumoniae, Mycoplasma pneumoniae, and Legionella pneumophila). "Furthermore, the revealed mechanism of the METTL3/NEAT1/CTCF/MUC19 axis provides new theoretical knowledge for bacterial pneumonia treatment and furnishes evidence for future therapeutic direction." (PMID 38757482, 2024).
benign prostatic hyperplasia (1 paper, 2019). A non-cancerous nodular enlargement of the prostate gland. "We detected the expression levels of NEAT1 in a total of 16 benign prostatic hyperplasia tissues (BPH), 30 matched adjacent healthy control (HC) tissues and 30 PCa tissues, as well as PCa cell lines PC-3, DU-145, LNCaP and normal prostate epithelial cell line RWPE-1." (PMID 31481527, 2019).
biliary tract cancer (1 paper, 2017). "Thus further rigorous studies with more samples are warranted to explore the role of NEAT1 in gallbladder carcinoma and biliary tract cancer." (PMID 28118609, 2017). "Since there were only three BTC-related and one GBC-related lncRNA expression datasets available in this study, we did not generate SROC curves to assess the diagnostic role of NEAT1 in gallbladder carcinoma and biliary tract cancer." (PMID 28118609, 2017).
brain tumor (1 paper, 2024). "Additionally, experiments were conducted in situ on brain tumors to investigate the impact of NEAT1 knockdown on tumor growth and survival." (PMID 39453684, 2024). "Consequently, we propose that the NEAT1/miR‐454‐3p axis significantly contributes to the emergence of chemotherapy resistance in GBM, and our study offers valuable insights into potential targets and developing therapeutic approaches for managing this aggressive brain tumor." (PMID 39453684, 2024).
Burkitt lymphoma (1 paper, 2017). A rare form of malignant mature B-cell non-Hodgkin lymphoma.
cerebral infarction (1 paper, 2024). An ischemic condition of the brain, producing a persistent focal neurological deficit in the area of distribution of the cerebral arteries. "To investigate the effect of ASO NEAT1 on cerebral infarction, we measured cortical cerebral blood flow and neurological deficits after MCAO injury." (PMID 38212456, 2024).
childhood leukemia (1 paper, 2023). An acute or chronic leukemia that occurs during childhood. "Moreover, NEAT1 has been previously implicated with chemoresistance in cancer, and both NEAT1 and MALAT1 have been associated with poor prognosis in childhood leukemia." (PMID 37528411, 2023).
chronic heart failure (1 paper, 2022). "In previous study, NEAT1 was reported as an unfavorable prognostic factor in chronic heart failure patients by log-rank test and ROC analysis." (PMID 35096206, 2022).
chronic inflammatory demyelinating polyradiculoneuropathies (1 paper, 2025). "NEAT1 expression is significantly upregulated in the PBMCs of patients with acute/chronic inflammatory demyelinating polyradiculoneuropathies (AIDP/CIDP)." (PMID 40362651, 2025).
chronic kidney disease (1 paper, 2024). Impairment of the renal function secondary to chronic kidney damage persisting for three or more months. "Through an in vitro osteogenic medium culture model and an in vivo adenine diet-induced chronic kidney disease model, we confirmed that NEAT1 promotes calcium accumulation in VSMCs, suggesting that NEAT1 upregulation in AS may contribute to arterial calcification." (PMID 38646788, 2024).
cutaneous squamous cell carcinoma (1 paper, 2022). "This study investigated whether lncRNA NEAT1 could inhibit the proliferation of cutaneous squamous cell carcinoma (CSCC) cells by targeting miR-342-3p/CUL4B, thereby affecting the occurrence and development of CSCC." (PMID 35909905, 2022).
dementia (1 paper, 2020). Loss of intellectual abilities interfering with an individual's social and occupational functions. "Valproic acid was identified as a potential therapeutic agent that may regulate the mutual switch genes shared among the dementias (PDE4DIP, NEAT1, LPIN3, ADCYAP1, CCDC136, and ITPKB)." (PMID 32471155, 2020).
disc degeneration (1 paper, 2021). "Thus, we speculated that lncRNA NEAT1 may affect the disc degeneration." (PMID 33478594, 2021).
female infertility (1 paper, 2023). Diminished or absent ability of a female to achieve conception. "LncRNA Neat1 is highly expressed in the corpus luteum and the deletion of lncRNA Neat1 induced partial defects of corpus luteum and stochastic female infertility." (PMID 37612724, 2023).
glaucoma (1 paper, 2023). Increased pressure in the eyeball due to obstruction of the outflow of aqueous humor. "Analysis of a circRNA–miRNA–mRNA interaction network found that aberrant expression of hsa_circ_0000745 in patients with glaucoma may regulate NEAT1 expression through hsa-miR-4659a-3p and hsa-miR-6873-3p." (PMID 37805546, 2023). "Although the specific roles of NEAT1 in glaucoma and the nervous system remain unclear, the results of the present study offer useful information for future explorations of the role of hsa_circ_0000745 in the pathogenesis of glaucoma." (PMID 37805546, 2023). "Analysis of a circRNA–miRNA–mRNA interaction network found that hsa_circ_0000745 and DEcircRNAs could potentially form a regulatory relationship with ARG1 and NEAT1 through the miRNAs, which may affect immune cell function, thereby promoting the development of glaucoma." (PMID 37805546, 2023). "Database analysis revealed that seven host genes (NEAT1, SAMD12, KDM5D, ZFY, EIF1AY, TXLNGY, and DDX3Y) of nine DEcircRNAs were also differentially expressed in blood samples of patients with glaucoma, and the trend of differential expression of circRNAs and host genes was consistent." (PMID 37805546, 2023).
HCMV infection (1 paper, 2024). "A small increase in paraspeckle number was observed during HSV-1 infection although these did not increase in size, whereas a more diffuse NEAT1 staining was observed during HCMV infection." (PMID 39592606, 2024).
hemorrhagic fever (1 paper, 2024). An infectious disease caused by certain viruses or bacteria that can damage the walls of tiny blood vessels, making them leak, and can hamper the blood's ability to clot and cause severe, life-threatening illness. "Conversely, the specific depletion of NEAT1 has been associated with severe hemorrhagic fevers, suggesting its potential utility as a diagnostic biomarker." (PMID 38542512, 2024).
hepatitis C (1 paper, 2024).
herpesvirus infection (1 paper, 2018). "Taken together, NEAT1 regulates the innate immune response mechanism upon herpesvirus infection by NEAT1 and SFPQ cooperative mechanisms through the transcriptional regulation of numerous antiviral genes." (PMID 29706968, 2018). "Upon herpesvirus infection, host lncRNAs, such as nuclear paraspeckle assembly transcript 1, negative regulator of antiviral, and B-cell integration cluster have been functionally characterized as negative or positive antiviral regulators in the immune response." (PMID 29706968, 2018).
ichthyosis (1 paper, 2023). Disorders of cornification that are characterized by visible scaling and/or hyperkeratosis of most or all of the skin. "We found that NEAT1 is upregulated in Ichthyosis lamellar human samples and in Alox12B KO mice, a mouse model resembling this skin disease." (PMID 37365156, 2023).
intervertebral disc degeneration (1 paper, 2021). "This study aimed to assess the role and mechanism of lncRNA NEAT1 in intervertebral disc degeneration (IVD)." (PMID 33478594, 2021).